MTHFS (methenyltetrahydrofolate synthetase)
Description:
Contributes to tetrahydrofolate metabolism. Helps regulate carbon flow through the folate-dependent one-carbon metabolic network that supplies carbon for the biosynthesis of purines, thymidine and amino acids. Catalyzes the irreversible conversion of 5-formyltetrahydrofolate (5-FTHF) to yield 5,10-methenyltetrahydrofolate.
Synonyms: HsT19268; NEDMEHM
Tractability: Small molecule: a structure with a bound ligand is known; it has a binding pocket of medium quality. PROTAC: ubiquitination databases record sites on it; its protein half-life has been measured.
Gene: Protein-coding gene on chromosome 15 (79,833,585 to 79,897,379, reverse strand). Ensembl gene ENSG00000136371.
Subcellular location: Cytoplasm
Subcellular location (Human Protein Atlas): Cytosol
Pathways (Reactome):
Metabolism: Metabolism of folate and pterines
Gene Ontology:
Molecular function: 5-formyltetrahydrofolate cyclo-ligase activity; ATP binding; folic acid binding; protein binding
Biological process: folic acid catabolic process; tetrahydrofolate interconversion; tetrahydrofolate metabolic process; folic acid metabolic process; folic acid-containing compound biosynthetic process; formate metabolic process
Cellular component: cytoplasm; cytosol; mitochondrial matrix; mitochondrion
Genetic constraint (gnomAD): Loss-of-function variants: 8 observed, 14.55 expected, observed/expected ratio (o/e) 0.55, 90% interval 0.32 to 0.99. The upper end of that interval is the gene's LOEUF score, 0.99, which puts it in group 4 of 6, group 1 being the genes least tolerant of losing a copy. Missense variants: 252 observed, 251.32 expected, observed/expected ratio (o/e) 1, 90% interval 0.9 to 1.11. Synonymous variants: 100 observed, 90.37 expected, observed/expected ratio (o/e) 1.11, 90% interval 0.94 to 1.31.
Homologues: Orthologues: macaque MTHFS (92% identical), dog MTHFS (85% identical), mouse Mthfs (82% identical), mouse Mthfsl (82% identical), pig MTHFS (82% identical), chimpanzee MTHFS (80% identical), rat Mthfs (79% identical), guinea pig MTHFS (64% identical), zebrafish mthfs (59% identical), tropical clawed frog mthfs (55% identical), Caenorhabditis elegans Y106G6E.4 (36% identical), Drosophila melanogaster Mthfs (33% identical). Paralogues in human: ATP5IF1 (8% identical).
Diseases named in the same sentence as MTHFS in open-access papers:
MTHFS is named in the same sentence as 22 diseases in open-access papers, as found by Europe PMC text mining. Sharing a sentence is not in itself a finding about the gene and the disease. The quoted sentences say what the papers report.
chronic kidney disease (2 papers, 2010 to 2013). Impairment of the renal function secondary to chronic kidney damage persisting for three or more months. "The product of MTHFS catalyzes the conversion of 5-formyltetrahydrofolate to 5,10-methenyltetrahydrofolate and a genome-wide association study reported an association between a variant in this gene and chronic kidney disease." (PMID 23552396, 2013). "Focusing upon quantitative renal phenotypes, a recent GWA study and a subsequent replication study identified variants in the 5,10-methenyltetrahydrofolate synthetase (MTHFS) gene to be associated with chronic kidney disease (CKD; defined as GFR < 60 ml/min/1.73 m2)." (PMID 20222955, 2010).
congenital heart defects (2 papers, 2021 to 2023). "Of note, the lead MTHFS SNP in infants, rs12438477, was previously shown to increase the risk of congenital heart defects by 6.76-fold (95% CI [2.56,17.89]) among infants with the AA genotype and SSRI exposure." (PMID 36672920, 2023). "Furthermore, genetic variants of SHMT1, BHMT, MGST1, MGMT, MTHFS, GNMT, and TRDMT1 were associated with an increased risk of congenital heart defects after prenatal antidepressant exposure." (PMID 33981330, 2021).
epilepsy (2 papers, 2023 to 2025). A brain disorder characterized by episodes of abnormally increased neuronal discharge resulting in transient episodes of sensory or motor neurological dysfunction, or psychic dysfunction. "MTHFS deficiency can present with varying degrees of neurodevelopmental abnormalities, ranging from mild GDD to refractory epilepsy to SUDEP." (PMID 37795244, 2023).
Athetosis (1 paper, 2023). A slow, continuous, involuntary writhing movement that prevents maintenance of a stable posture. "In conclusion, we reported three new cases of MTHFS deficiency and the process of diagnosis and treatment, which expands the phenotype spectrum with the novel features of athetosis, eczema, and recurrent diarrhea." (PMID 37795244, 2023).
folate deficiency (1 paper, 2023). A nutritional condition produced by a deficiency of FOLIC ACID in the diet. "Fourth, MTHFS deficiency also exhibits an intramitochondrial folate deficiency, which would shunt intramitochondrial translation of mitochondrial methionyl-tRNA and lead to secondary mitochondrial dysfunction, resulting in deficient energy for brain development." (PMID 37795244, 2023).
hepatocellular carcinoma (1 paper, 2023). A malignant tumor that arises from hepatocytes. "created a novel Hepatocellular Carcinoma prediction model that integrates 7 GlnMgs, including SLC1A5, GAPDH, SLC38A1, SLC38A7, FTCD, MTHFS, and GOT2 might be utilized to predict prognosis in HCC." (PMID 37377916, 2023).
homocystinuria (1 paper, 2023). An autosomal recessive inherited metabolic disorder caused by mutations in the CBS, MTHFR, MTR, and MTRR genes. "The fifth patient with MTHFS deficiency is a girl characterized by similar features, including microcephaly, GDD, hypertonia, seizure, and cerebral hypomyelination, while she was initially diagnosed with homocystinuria." (PMID 37795244, 2023).
cancer (3 papers, 2007 to 2024). A tumor composed of atypical neoplastic, often pleomorphic cells that invade other tissues. "Methenyltetrahydrofolate synthetase (MTHFS) catalyses 5‐formyltetrahydrofolate (5‐f‐THF) conversion to 5,10‐methenyltetrahydrofolate (5,10‐CH‐THF) and then participates in the synthesis of purine, which is upregulated in various cancers." (PMID 38279895, 2024).
tumor (3 papers, 2021 to 2024). "The results of single-cell data suggested that SHMT2, ATIC and MTHFS were mainly expressed in tumor cells." (PMID 38625586, 2024). "Regarding MTHFS (methenyltetrahydrofolate synthetase) and FTCD (formimidoyltransferase cyclodeaminase), both genes participate in the metabolism of cofactors and vitamins and are downregulated in HCC with a higher tumor stage." (PMID 36250026, 2022).
kidney disease (1 paper, 2008). "This genome-wide association study provides unbiased information implicating MTHFS as a candidate gene for kidney disease." (PMID 18522750, 2008). "Further work is needed to fully characterize the association of genetic variants in MTHFS with kidney disease." (PMID 18522750, 2008). "In summary, the association of SNP rs6495446 in MTHFS with CKD was replicated in an independent study sample of white ARIC participants, constituting the first GWAS of kidney disease traits including both discovery and replication." (PMID 18522750, 2008). "Although this observation does not allow for the conclusion that altered MTHFS mRNA levels associated with rs6495446 are causally related to kidney disease, it provides some functional evidence for rs6495446 or a variant in LD with it." (PMID 18522750, 2008). "However, the SNP rs6495446 (MTHFS), which replicated among white ARIC participants for the association with CKD, showed a hazard ratio of 1.13 per each increase in C allele for kidney disease progression (95% CI 1.01–1.26, p = 0.041)." (PMID 18522750, 2008).
MTHFS also shares sentences with these, for which no sentence is quoted: lung carcinoma (2 papers); breast carcinoma (1); cerebral folate transport deficiency (1); eczema (1); endothelial dysfunction (1); glioma (1); infection (1); major depression (1); microcephaly (1); Parkinson disease (1); schizophrenia (1); small cell lung carcinoma (1).